CRP (C-reactive protein)
Diseases named in the same sentence as CRP in open-access papers (continued):
Sharing a sentence is not in itself a finding about the gene and the disease.
cancer (continued). "Recently, a number of inflammatory indices, including C-reactive protein (CRP), neutrophil-to-lymphocyte ratio (NLR), platelet-to-lymphocyte ratio (PLR), and modified Glasgow prognostic score, have been considered as independent prognosis factors in patients with cancer." (PMID 36718344, 2022). "While a direct role for cancer cell–induced CRP in immune cell proliferation has not been found, several reports suggest that CRP may play a role in T cell proliferation." (PMID 35385679, 2022). "Therefore, more and more inflammatory and/or nutritional predictors, such as C-reactive protein (CRP), neutrophil to lymphocyte ratio (NLR), albumin (ALB), and CRP to ALB ratio (CAR), have been applied either alone or in combination to various cancers in recent years." (PMID 34676808, 2022). "According to some reports, CRP/ALB ratio may have a prognostic value in cancer, unfortunately, we were not able to confirm this in our patient’s cohort." (PMID 35174082, 2022). "Although all patients had undergone chest CT scans and routine blood examinations to rule out the presence of metastasis and/or other cancers, other chronic disease that may increase CRP levels were not taken into consideration due to the lack of information." (PMID 36358634, 2022). "CRP, a non-specific marker of inflammation, can be increased in malignancies, and its role as a predictive biomarker of survival has been confirmed in certain adult cancers." (PMID 35804835, 2022). "In addition, elevated CRP levels in patients with advanced or active cancers have not been evaluated in this study." (PMID 36079002, 2022). "In addition, our results suggest that CRP and LHR can predict the survival of patients with cancer." (PMID 35752767, 2022). "A significant difference was found in age, fever, no symptoms, elevation of white blood cell count and C-reactive protein level, family history of cancer, air bronchogram, interlobular fissure bulging, satellite lesions, and CT attenuation value (all p < 0.05)." (PMID 36461012, 2022). "There is no rigorous evidence on which CRP or NLR performs better in prognostication in cancer." (PMID 34350956, 2021). "We examined the survival predictability of QLQ-C15-PAL scores and inflammatory biomarkers in terminally ill patients with cancer and found that the QLQ-C15-PAL dyspnea and fatigue scores could be independent prognostic indicators comparable to the inflammatory biomarkers CRP, Alb, and NLR." (PMID 33757453, 2021). "Nevertheless, in the scenario of cancer-related inflammation, we could not detect a robust reduction in IL-6 and CRP levels in the patients with cancer and cachexia after n-3 supplementation." (PMID 35174197, 2021). "Researches showed editing role in the pathogenesis of cancer and indicated its relation with mediators such as tumour necrosis factor-α (TNF-α), soluble TNF-related apoptosis-inducing ligand (sTRAIL), interleukin-6 (IL-6), pentraxin-3 (PTX-3), procalcitonin (PCT), and Creactive protein (CRP) levels." (PMID 33776564, 2021). "In such a follow-up study, additional inflammation parameters to CRP, such as TNF-α, IFN-γ, and/or IL-1, should be included to gain more insight into the potential mechanistic links between complement activation and pro-inflammatory processes in patients with cancer cachexia." (PMID 34830921, 2021). "Although an increased level of CRP might be nonspecific, some studies have found that patients with cancer have a higher CRP level than healthy people." (PMID 34992504, 2021). "There was no statistical variation among the cancer groups when compared to the CRP levels." (PMID 33776564, 2021). "In addition, studies have shown that the integration of these biochemical indicators such as the modified Glasgow Prognosis Score (mGPS), C-reactive protein to albumin ratio (CAR), and neutrophil to lymphocyte ratio (NLR) can effectively improve the accuracy of cancer prognosis prediction." (PMID 34150609, 2021).
cancer (continued). "The prognostic value of the CRP to albumin ratio (CAR) among older adults with cancer is not known." (PMID 34830936, 2021). "Given the association between the immune system and the development and progression of cancer, it is not surprising that there would be interest as to whether CRP, as a measure of immune response, could help determine cancer prognosis." (PMID 34926085, 2021). "However, CRP, as a general marker of inflammation, is unlikely to capture the specific inflammatory mediating pathways linking inflammation to cancer development and progression." (PMID 32978716, 2021). "However, on multivariate analysis, both CRP and fibrinogen were not independent predictors for cancer mortality." (PMID 34210304, 2021). "CRP is not specific to cancer, but it is also related to non-cancer diseases." (PMID 34350956, 2021). "Cancer cells could also produce several cytokines and chemokines, thus leading to inflammatory cell infiltration into the tumor microenvironment (TME) and increasing the serum CRP concentration." (PMID 33270989, 2021). "C-reactive protein (CRP) is an acute-phase protein primarily produced in response to systemic inflammation that plays an important role in the development and progression of a variety of cancers due to the upregulation of various cytokines and pro-angiogenic factors." (PMID 34070592, 2021). "We investigated the kinetics of CRP, PCT, IL-6 and MR-proADM in a cohort of consecutive febrile patients with cancer in order to test the hypothesis that higher plasma concentrations and the absence of a rapid decrease in peak values would be associated with disease severity." (PMID 34828740, 2021). "The noncausal involvement of circulating CRP in cancer was not entirely unexpected." (PMID 32477370, 2020). "In addition, since systemic inflammatory response to cancer has been described as a poor prognostic factor in NSCLC, we correlated the serum C-reactive protein (CRP) level and neutrophil to lymphocyte ratio (NLR) as most investigated inflammatory markers with PFS and OS." (PMID 33121520, 2020). "Survival analysis in American Joint Committee on Cancer stages I–III demonstrated associations between 25OHD tertile and CRC mortality (HR=0.69; 95% CI 0.46 to 0.91) and all-cause mortality (HR=0.68; 95% CI 0.50 to 0.85), and was independent of CRP." (PMID 31023832, 2020). "Hence, higher values of the CRP/albumin ratio in the CRP pointed to a relatively lower protein status in cancer cachexia albeit albumin concentrations were not below the reference value." (PMID 32083092, 2020). "A report indicated that cancer stages were related to CRP level and not to PCT level." (PMID 32908505, 2020). "Plasma CRP is not selective for any cancer type or tissue involving cancer." (PMID 33324413, 2020). "The cancer group has a higher CRP titer, which did not lead to an increase in mortality." (PMID 33334375, 2020). "A review concluded that cancer patients generally had higher CRP levels than controls, but as 81 of the 90 studies were cross-sectional we do not know whether the higher CRP levels occurred before the cancer or vice versa." (PMID 32209087, 2020). "CRP, an acute-phase protein synthesized in response to systemic inflammation, has also been well studied as a marker of overall inflammatory response, however it has not been well characterized in the context of cancer mortality disparities." (PMID 31448052, 2019). "Consequently, patients with aberrant or over-represented pathologic myeloid effectors, such as those with cancer, AKI, etc., might benefit from specific lowering of CRP." (PMID 31620123, 2019). "Many studies have shown that serum inflammatory markers, such as C-reactive protein (CRP), the NLR, the platelet-to-lymphocyte ratio, the Glasgow Prognostic Score (GPS), and the systemic immune-inflammation index, are related to the clinical outcomes of cancer patients." (PMID 31677642, 2019). "We detected no C-reactive protein in the cancer cell culture supernatants by ELISA." (PMID 30692520, 2019).
cancer (continued). "The inherent invasive characteristics of cancer might be more import when it comes to relapse or not, thus serum CRP level as well as other systemic inflammation markers might serve as an indicator for more intensive therapy." (PMID 31260491, 2019). "In our cohort, other known prognostic factors (pT stage, grade, Hb, neutrophil, LDH, CRP, Na, corrected calcium) could not show significant correlation with cancer-specific survival (CSS), while FABP7 could be a prognostic marker." (PMID 30442117, 2018). "CRP‐lowering drugs, such as COX inhibitors and lipid‐lowering agents, have already been confirmed as effective therapeutic targets for patients undergoing cardiovascular therapy, providing promising clues for theoretical efficacy in cancer prevention and therapy." (PMID 29193777, 2018). "Collectively, this cross-sectional analysis suggests a synergism among the CRP, TST, and waist circumference variables among cancer survivors that differ from the expected linear CRP and waist circumference (central adiposity) relationship observed in cancer-free adults." (PMID 29789774, 2018). "However, some studies have suggested that neither NLR nor C-reactive protein levels are accurate prognostic markers for cancer progression or overall survival." (PMID 28430597, 2017). "Notably, preoperative C-reactive protein (CRP), which represents a marker of systemic inflammatory reactions, has been widely reported as a prognostic factor for poor survival in patients with various cancer types, including STS." (PMID 29228679, 2017). "Additionally, we think that CRP is not necessarily a characteristic parameter in cancer cachexia because it is not routinely measured in clinical practice, in Germany usually only if indicated." (PMID 28193264, 2017). "CRP is considered a negative marker for overall survival of cancer patients." (PMID 28915665, 2017). "In women, serum CRP was not suggested to correlate with cancer mortality (P = 0.59)." (PMID 26632325, 2016). "Neither in other cancer nor in ESCC had the significance of CRP/PNI been investigated before." (PMID 27557504, 2016). "The multivariate analysis including age at operation, preoperative serum CRP level, RNS sum, A component, and presence of h showed that only the RNS sum (HR, 9.05; 95 % CI, 2.11–63.9; P = 0.0019) was an independent predictive factor for postoperative cancer recurrence." (PMID 26219992, 2016). "And recently, Debiane analysed 114 critically ill adult patients with cancer (51.8% solid cancer, 48.2% haematological cancer) and found an AUC of 0.77 (95% CI 0.67 to 0.87) for PCT testing for 60-day mortality prediction, which was superior compared to CRP testing (AUC 0.62, 95% CI 0.48–0.75)." (PMID 25861154, 2015). "CRP is a non-specific acute-phase protein that rises on acute infection as well as tissue trauma, chronic inflammatory disease, myocardial infarction, surgery and cancer." (PMID 25340395, 2014). "Although CRP and other serum proteins are also important indicators of cancer-related inflammation, these factors were not routinely measured at our hospital prior to 2006; therefore, the long-term predictive value of these factors could not be assessed." (PMID 24718309, 2014). "It is now well recognized that -beyond the C-Reactive Protein (CRP), which is probably the main serum marker for inflammation- cell count for white blood cells (WBC) and polymorphonuclear cells (PMN) represents a good support for postoperative immunological evaluation of cancer patients." (PMID 24040252, 2013). "Although rising opinions support the role of CRP as a predictor of lower survival rates in patients with several cancers, including CRC, no definitive results have been published regarding its effective value as an independent variable on postsurgical recovery." (PMID 24040252, 2013).
cancer (continued). "Various markers of systemic inflammatory response, including cytokines, C-reactive protein (CRP), and absolute blood neutrophil or lymphocyte count as well as their ratio such as neutrophil-to-lymphocyte ratio (NLR) have been investigated for their prognostic roles in certain cancer populations." (PMID 23516447, 2013). "In this regard, we analyzed this relationship in a large database of cancer patients given IVC therapy; moreover, we examined the dependence of plasma ascorbate concentrations in patients with localized and metastatic tumors on C-reactive protein levels and tumor marker levels." (PMID 23947403, 2013). "We further propose that liver and cancer mortality are mediated via CRP dependent pathways but CVD mortality may not be dependent upon CRP." (PMID 22514624, 2012). "Finally, our findings demonstrate that the course of CRP during the first week of antibiotic therapy was similar in neutropenic and non-neutropenic septic critically ill cancer patients." (PMID 21595932, 2011). "Moreover, we found that septic neutropenic cancer patients had significantly higher CRP concentrations in comparison with non-neutropenic patients at ICU admission." (PMID 21595932, 2011). "Furthermore, higher CRP levels were observed across all categories of all anthropometric measures in CRC cases diagnosed within the first four years of follow‐up compared to those diagnosed later, suggesting a potential influence of preclinical cancer on CRP concentrations." (PMID 39791283, 2025). "However, human CRP induced both the expression of PD‐L1 and the activation of STAT3 in mouse bone marrow‐derived macrophages, similar to HMDMs (data not shown); therefore, validated animal models are needed to study the biological functions of CRP in various diseases, including cancer." (PMID 39564003, 2024). "We therefore tested the hypothesis that elevated plasma CRP, IL‐6 and YKL‐40, alone and as a combined biomarker score, could identify groups of patients with nonspecific signs and symptoms of cancer, with high cancer risk and poor survival." (PMID 36440611, 2023). "Indeed, the combination of AFP and CRP in ICI outcome prediction in HCC is rational at the mechanism level; CRP, an acute-phase protein, is a widely-recognized systemic marker of inflammation induced by cancer, and inflammation can contribute to tumorigenesis and disease progression." (PMID 37268978, 2023). "Increased levels of some inflammatory markers were observed in firefighters, e.g., pro-inflammatory cytokines or C-reactive protein (CRP), which may lead to occurrence local, acute inflammation that promotes a systemic inflammatory response, and thus may develop of cancer or other diseases." (PMID 36094704, 2022). "However, whether there are associations between appetite and albumin, or between appetite and CRP, that differ between men and women has not previously been studied in a palliative cancer population." (PMID 35629338, 2022). "In addition, the Glasgow prognostic score (GPS), which uses C-reactive protein (CRP) and serum albumin cutoff values of 1.0 mg/dL and 3.5 g/dL, respectively, has been shown as an important and useful nutritional assessment tool for predicting prognosis in patients with malignant tumors." (PMID 35565221, 2022). "In addition, the Glasgow prognostic score (GPS), defined based on C-reactive protein (CRP; 1.0 mg/dL) and serum albumin (3.5 g/dL) levels, was shown to be an important and useful nutritional assessment tool for predicting prognosis in patients with malignant tumors." (PMID 36358711, 2022). "Although CRP had been reported as a poor prognostic factor of CLL, our results identified negative associations between CRP and incident cancer events of CLL during the follow-up, which might indicate preclinical patients had been undergoing immune dysfunction." (PMID 36117174, 2022).
cancer (continued). "Biochemical thresholds that reflect low-grade inflammation, serum CRP >10mg/L and low serum albumin concentrations <35 g/L, combined in the Glasgow Prognostic Score (GPS) remained independently prognostic for patients without an underlying diagnosis of cancer at 6-months post diagnosis of acute PE." (PMID 34962922, 2021). "However, inflammatory markers are not a useful rule-out test for cancer, as with a sensitivity of 46.1% for CRP, 43.6% for ESR and 49.7% for PV, roughly half of the tested patients with cancer had a normal inflammatory marker test in the 1 year before diagnosis." (PMID 31015558, 2019). "However, because CRP shows a nonspecific increase in various situations, including inflammation, it could not be used as a sole biomarker for cancer." (PMID 30411459, 2019). "However, in most reports of CRP and cancer prognosis, survival was not the primary study objective." (PMID 30138391, 2018). "However, CRP is not routinely measured as part of pretreatment evaluation of cancers." (PMID 30631798, 2018). "It was previously reported that various inflammation-based prognostic scores, such as C-reactive protein (CRP), Glasgow prognostic score (GPS), platelet-to-lymphocyte ratio (PLR), and neutrophil-to-lymphocyte ratio (NLR) might be useful for predicting survival in patients with a malignant neoplasm." (PMID 29581844, 2018). "In subgroup analysis for patients without malignancy disease, the relative risk for mortality was also associated with APACHE II score (hazard ratio (HR) = 1.04, 95% CI = 1.03–1.06, p < 0.001) and CRP/albumin ratio (HR = 1.39, 95% CI = 1.02–1.90, p = 0.04 for high CRP/albumin ratio)." (PMID 30297655, 2018). "Furthermore, regarding the CRP cutoff, we have tested it at 10 mg/L, which may appear to be low for advanced cancer patients, and may explain why CRP was not statistically significant in our multivariate analysis." (PMID 21406082, 2011). "Biochemical parameters, such as C-reactive protein and albumin (combined to form the modified Glasgow Prognostic Score, mGPS), alkaline phosphatase (Alk phos), γ-glutamyl transferase (GGT) and serum calcium have been reported to be associated with cancer and non-cancer mortality." (PMID 20717110, 2010). "Also, elevated CRP levels in GBC patients reflect an underlying systemic inflammatory response, a pattern consistently reported in previous GBC studies as well as other malignancies, indicating that this is a general marker of cancer-related inflammation rather than a GBC-specific signature." (PMID 40941022, 2025). "In patients without malignancy, PCT achieved the highest AUC (0.849), with MDW (0.834) and CRP (0.826) following." (PMID 41303127, 2025). "CRP levels did not independently predict survival in PAN, suggesting differences in the inflammatory milieu between cancer types." (PMID 39330032, 2024). "In our study, gender, age, CRP, AST, ALT, and total protein were not shown to be independent factors of cancer cachexia." (PMID 39272892, 2024). "Third, current clinical practice does not routinely check baseline CRP level before IMDC diagnosis, excluding the possibility of exploring the role of CRP at different stages of the cancer treatment course." (PMID 37476185, 2023). "CRP, IL‐6 and YKL‐40 were elevated in 44%, 60% and 45% of the cancer patients, and in 15%, 33% and 25% of the patients without cancer." (PMID 36440611, 2023). "In patients with cancer, BNP can be elevated in absence of clinical HF and positively correlates with high-sensitivity C-reactive protein (hsCRP), suggesting a relationship with cancer-related inflammation." (PMID 36790618, 2023). "There is also good evidence that C-reactive protein (CRP) and the NLR are both sensitive and reliable markers of systemic inflammation in cancer patients; unfortunately, CRP measurements are not routinely performed for our palliative cancer patients." (PMID 35585628, 2022).